IGF1 (insulin like growth factor 1)
Diseases named in the same sentence as IGF1 in open-access papers (continued):
Sharing a sentence is not in itself a finding about the gene and the disease.
Stroke (continued). "Compared to nimodipine alone, Tongxinluo combined with nimodipine significantly reduces serum levels of hs-CRP and Tau protein, increases IGF-1 levels, and improves neurological deficit symptoms in stroke patients, with no serious adverse reactions observed during the treatment period." (PMID 40761406, 2025). "Therefore, the administration of cGP restores the equilibrium between IGF-1 and cGP, or simply displaces IGF-1 from the IGFBP-3 binding complex, thereby improving cognitive function, promoting recovery from stroke, and normalising blood pressure (in hypertensive rats)." (PMID 36770687, 2023). "Moreover, increased IGF-1 and IGF-1R was shown to inhibit inflammatory processes, mainly through inhibiting the expression of proinflammatory cytokines, reducing neurodegeneration and secondary low immune function after stroke." (PMID 27527872, 2016). "Interestingly, while NaB significantly increases IGF-1 in peripheral tissues in the post stroke animal, there was no elevation of IGF-1 in the brain with this treatment." (PMID 27905989, 2016). "In addition, BECs secrete neurotrophins, such as brain-derived neurotrophic factor (BDNF), insulin-like growth factor 1 (IGF1), and vascular endothelial growth factor (VEGF), to maintain normal brain homeostasis, suggesting that neurotrophic factors are a potent drug candidate for stroke therapy." (PMID 37458258, 2023). "Moreover, while previous studies have assessed non-linearity by examining percentiles of IGF-1, the possibility of dose–response association of IGF-1 with the risk of dementia, stroke, and PD has not been fully characterized in a large general population sample." (PMID 37608387, 2023). "However, the role of IGF-1 in acute or silent stroke in SCD has never been explored." (PMID 36979670, 2023). "Additionally, these data also show that in addition to its well-known anti-inflammatory actions, NaB may exert a biphasic effect after stroke, operating initially to reduce BBB permeability and oxidative stress in the brain, and later, elevating IGF-1 expression in peripheral tissues." (PMID 27905989, 2016). "Silymarin raised cortical TNFα, IL4, IL10, IGF1, BDNF, and CX3CL1 levels in the HFD group with stroke, while the striatum did not present relevant differences." (PMID 39624169, 2024). "Although these literature data suggest that IGF-1 has prognostic value, our present findings indicate that IGF-1 plasma level was not affected by three-week rehabilitation following stroke." (PMID 37371326, 2023).
pituitary adenoma (158 papers, 2007 to 2026). "In this article focused on GH&PRL pituitary adenomas, we found that a Knosp grade >2, and higher serum GH and IGF-1 levels were associated with a lower probability of surgical cure in these tumors." (PMID 40590355, 2025). "In summary, overproduction of GH and IGF-1 due to pituitary adenoma not only causes distinctive cosmetic alterations but also results in multisystem health issues." (PMID 39331882, 2024). "For this reason, IGF-1 upregulation is thought to be the primary mechanism underlying the co-occurrence of GH-secreting pituitary adenomas and intracranial meningiomas." (PMID 38919490, 2024). "BMD Z score was negatively correlated with disease duration and IGF-1 burden in patients with GH-secreting pituitary adenomas, and IGF-1 burden was an independent risk factor for reduced lumbar-spine BMD Z score." (PMID 31781204, 2019). "While the usual cause of acromegalic gigantism is a GH-secreting pituitary adenoma, resulting in elevated GH- and insulin-like growth factor 1 (IGF-1) levels, we should remember other conditions with tall stature, either as a normal variant or part of a syndrome with no abnormalities in the GH axis." (PMID 33543431, 2021). "Following thyroidectomy, the patient experienced the regression of his pituitary adenoma and the normalization of his IGF-1 levels." (PMID 41358366, 2026). "The disease is characterized by GH excess, most commonly originating from a pituitary adenoma, and elevated levels of IGF-1, its primary mediator." (PMID 39821533, 2025). "The disease is characterized by excessive secretion of growth hormone (GH) and elevated levels of insulin-like growth factor 1 (IGF-1), typically caused by a GH-secreting pituitary adenoma." (PMID 40727910, 2025). "Hormone assays such as plasma ACTH, serum cortisol, prolactin, GH, follicle-stimulating hormone (FSH), luteinizing hormone (LH), and insulin-like growth factor 1 (IGF-1) values which were done as a part of pituitary adenoma workup were analyzed." (PMID 39677352, 2024). "For instance, Iacovazzo's study assessed the correlation between the likelihood of a difficult airway occurrence and the Insulin-like Growth factor 1 (IGF-1) levels in patients with GH-producing pituitary adenoma." (PMID 39020308, 2024). "Growth hormone (GH)-secreting pituitary adenomas, marked by elevated levels of GH and IGF-1, account for approximately 12% of functional pituitary tumors." (PMID 38370349, 2024). "Nevertheless, pituitary adenomas in patients with gigantism are often highly secretory, leading to significantly elevated GH and IGF1 levels." (PMID 37891382, 2024). "GH-secreting pituitary adenomas can result in overproduction of IGF-1, while other types of PitNET can lead to IGF-1 deficiency due to their occupying effect." (PMID 38370349, 2024). "The Mean age at diagnosis, nadir GH, and pituitary adenoma size were similar between women and men, but the values of IGF-1 were lower in women, aspects encountered in our study as well." (PMID 37374352, 2023). "At the second stage, the IGF-1 level was additionally determined in 53 patients with hyperprolactinemia and pituitary adenoma (total 94 patients)." (PMID 38796756, 2023). "CONCLUSION: In real clinical practice the level of IGF-1 is studied only in 39% of cases in patients with pituitary adenoma and hyperprolactinemia." (PMID 38796756, 2023). "At the first stage of the study, the proportion of patients with pituitary adenoma and hyperprolactinemia with studied IGF-1 levels was determined, according to medical records." (PMID 38796756, 2023). "Diagnosis includes serum GH and IGF-1 levels, and obtaining an MRI pituitary protocol to assess for a functional pituitary adenoma." (PMID 35992136, 2022). "In almost all cases, this disease is due to a GH (growth hormone)-secreting pituitary adenoma leading to elevated growth hormone and insulin-like growth factor 1 (IGF-1) levels." (PMID 35359232, 2022).
pituitary adenoma (continued). "The role of miR-16 in regulating the GH/IGF1 axis represents a potential key point for further investigations within pituitary adenomas." (PMID 34484116, 2021). "This study was designed to investigate microstructural pathology in the cortex and white matter in growth hormone-secreting pituitary adenoma, which characterized by excessive secretion of GH and IGF-1." (PMID 33912457, 2021). "Growth hormone-secreting pituitary adenomas are characterized by excessive growth hormone (GH) and insulin-like growth factor-1 (IGF-1) secretion, which consequently results in a series of metabolic disorders." (PMID 31736874, 2019). "Based on our data, 15-Lox-1 highly expressed in GH-secreting pituitary adenoma which had the elevated level of IGF-1 as a consequence of the disease." (PMID 31288808, 2019). "Our previous study found significantly higher secretion of IGF-1 and growth hormones in the GH-secreting adenoma group than in the NF pituitary adenoma group." (PMID 31477080, 2019). "GH and IGF-1 levels in patients with GH-secreting pituitary adenomas were significantly higher than those in the control group (both p values <0.001)." (PMID 31781204, 2019). "PAS-LAR demonstrated significant reductions in IGF-1 levels and pituitary adenoma size." (PMID 38244140, 2024). "In summary, our study indicated that lower IGF‐1 and CRH levels, as well as serum potassium and sodium levels and blood glucose levels, were potentially associated with postoperative delirium in pituitary adenoma patients treated by endoscope‐assisted transsphenoidal surgery." (PMID 37137534, 2023). "Second, no longitudinal imaging data collected from patients with GH-secreting pituitary adenoma after surgery to study whether the decrease of serum level of GH/IGF-1 lead to the alteration of brain structure." (PMID 31967977, 2020). "Refractory pituitary adenoma and longer duration of physiological stimulation by the obviously increased GH and IGF-1 might lead to the larger bilateral ICAs distance." (PMID 32733381, 2020). "In vitro samples of primary cultures of somatotropinoma and rat pituitary adenoma cell line (GH3) showed that imatinib, a drug that causes growth failure in CML probably targeting GH or IGF-1 axis, inhibited GH secretion in a dose-independent manner and without affecting cell viability." (PMID 30210447, 2018). "Screening of endocrinopathy revealed GH excess with an elevated Insulin-like Growth Factor-1 (IGF-1) level and 7 mm pituitary adenoma." (PMID 40584159, 2025). "The research conducted on GH3 and GH4C1 rat pituitary adenoma cell lines showed that IGF1 improves somatotroph cell viability through the PI3K/AKT/mTOR pathway and the inhibitory effect of IGF1 on GH secretion via this pathway." (PMID 37446128, 2023). "Few studies reported the effects of growth hormone-secreting pituitary adenoma (GHPA) on uric acid (UA) metabolism and the relationship between growth hormone (GH)/insulin-like growth factor-1 (IGF-1) levels and UA are controversial." (PMID 37818085, 2023). "Growth hormone-secreting pituitary adenoma (GHPA) is characterized by increased growth hormone (GH) and insulin-like growth factor I (IGF-1) secretion." (PMID 35947334, 2022). "Current knowledge on the role of miRNAs and lncRNAs on the GH/IGF1 axis and IGF system in pituitary adenomas." (PMID 34484116, 2021). "So other factors must be involved in the pathogenesis of DTC in acromegalic patients, in addition to GH/IGF-1 excess, such as genetic or epigenetic modifications, like those already identified in the setting of PTC and GH-secreting pituitary adenoma." (PMID 25019383, 2014). "Biochemically, IGF-1 normalized within 6 months of total thyroidectomy, and an MRI demonstrated the progressive shrinkage of the pituitary adenoma, reducing to 8x6x5.5 mm at 1 year without neurosurgical intervention." (PMID 41358366, 2026).
pituitary adenoma (continued). "Clinical diagnosis of TSH/GH co-secreting pituitary adenoma was made based on elevated free T4, total T3, serum α-subunit, insulin-like growth factor-1 levels and non-suppressible GH levels after oral glucose loading." (PMID 34461869, 2021). "Against this background, it would be of interest to further investigate whether pituitary adenomas with GFAP cytokeratin co-expressing cells express NGF receptors and/or if they represent increasing neural elements upon the influence of IGF-1." (PMID 33001343, 2021). "Multiple linear regression analysis showed that IGF-1 burden was negatively correlated with the preoperative BMD Z score at L1 (r = −0.398, p=0.007, R = 0.631) and L1–L4 (r = −0.387, p=0.01, R = 0.619) in patients with GH-secreting pituitary adenoma." (PMID 31781204, 2019). "The median of IGF-1-SD-score of 46 patients with nonfunctioning pituitary adenomas and postoperative severe GHD was −1.44 with mean of −1.43 ± 1.36 (SD)." (PMID 22918542, 2013). "However, there is no understanding of the necessity to investigate the IGF-1 level in patients with hyperprolactinemia and a pituitary adenoma." (PMID 38796756, 2023).
lung carcinoma (155 papers, 1990 to 2026). "Elevated IGF1 is linked to increased risk of thyroid, colorectal, breast, prostate, and lung cancer." (PMID 40297587, 2025). "The lung cancer PRS was associated with lower levels of insulin-like growth factor-1 (IGF-1) (p = 8.58 × 10−18) and high-density lipoprotein (HDL) cholesterol (p = 3.94 × 10−17)." (PMID 33579919, 2021). "The upper limit of normal IGF-1 is associated with high breast, prostate, colorectal, and lung cancer risk in general population." (PMID 34530525, 2021). "Results were consistent in sensitivity analysis, except for suggestive evidence of a positive association between genetically predicted IGF‐1 levels and lung cancer in UK Biobank in the MR‐Egger analysis." (PMID 32717139, 2020). "High serum concentrations of IGF1 are associated with an increased risk of breast, prostate, colorectal, and lung cancers." (PMID 32565805, 2020). "One signaling pathway that has been implicated in lung cancer outcomes and resistance to targeted therapies is the insulin-like growth factor-1 (IGF-1) signaling pathway." (PMID 31393907, 2019). "Inverse associations of IGFBP3 circulating level with lung cancer, and of IGF1 and placental GH with epithelial ovarian cancer in women aged <55years at diagnosis have also been observed." (PMID 27552970, 2016). "It is unlikely that the IGF-1 pathway alone would explain entirely the observed increased colorectal and lung cancer risk associated with adult height." (PMID 27598322, 2016). "In lung cancer, elevated plasma levels of IGF-1 have been associated with an increased risk of the disease." (PMID 25944691, 2015). "Cancer mortality analysis of risk factors associated with all-cause and lung cancer mortality with integration of insulin like growth factor 1 and IGF binding protein 3 (IGFBP3)." (PMID 23405181, 2013). "Regardless, heavy smoking in cumulative dose would likely increase lung cancer risk by increasing carcinogen exposure long-term, while simultaneously increasing IGF1 or IGF2 levels or decreasing IGFBP3 levels." (PMID 22347413, 2012). "As lung cancer is one of the most malignant cancers, we conducted a meta-analysis in order to investigate the strength of association between circulating IGF-1 and IGFBP-3 levels and lung cancer." (PMID 23185474, 2012). "Risk of lung cancer in association with IGF1 (CA)n repeat genotype by different status of green tea consumption." (PMID 22347413, 2012). "The possibility of an association between smoking, IGF1 level and IGF1 genotype on lung cancer risk needs further investigation." (PMID 22347413, 2012). "In order to investigate the circulating IGF-1 concentration and lung cancer risk, the SMD 0.568 (95%CI: [-0.035, 1.171], P = 0.065) was calculated with the means and SDs supplied in the articles." (PMID 23185474, 2012). "For example, elevated plasma levels of IGF-1 and single nucleotide polymorphisms within the IGF axis are associated with an increased risk of lung cancer." (PMID 21464968, 2011). "Macrophages are crucial for the progression of numerous cancers, including lung cancer, and IGF-1 has long been associated with resistance to chemotherapy and increased neoplastic proliferation." (PMID 21699731, 2011). "While the expression of IGFBP-3 may not be completely absent, a decrease in its expression can cause an elevation in the local availability of IGF-1 in lung tissue, thereby increasing the risk of developing lung cancer." (PMID 38540176, 2024). "Studies have found that high IGF-1 levels in the blood may increase the risk of lung cancer, while high levels of circulating IGFBP-3 may decrease risk." (PMID 38540176, 2024). "However, Qian has reported positive associations of IGF-1 with breast, prostate, colorectum, melanoma, kidney, thyroid, and inverse associations with lung cancer in ever-smokers." (PMID 36329881, 2022). "To date, IGF-1 and lung cancer have been found to be associated in various ways." (PMID 34177367, 2021).
lung carcinoma (continued). "However, it is unlikely that the IGF1 gene alone would explain the observed increased lung cancer risk associated with adult height." (PMID 28949980, 2017). "Studies to date have investigated the association between IGF‐1 and lung cancer." (PMID 27734632, 2016). "However, elevations in the serum level of IGF1 are correlated with an increased risk for developing breast, colon, prostrate and lung cancer in mouse models." (PMID 24813441, 2014). "We also evaluated the effect of IGF1 on lung cancer risk by green tea consumption." (PMID 22347413, 2012). "Green tea drinkers with susceptible IGF1 genotypes have a reduced risk of lung cancer." (PMID 22347413, 2012). "Furthermore, elevated plasma levels of IGF-1 have been associated with an increased risk of lung cancer and high plasma levels of IGFBP3 have been associated with a reduced risk, although results from a meta-analysis did not recapitulate this association." (PMID 24212944, 2011). "The majority of lung cancers are caused by smoking, and smoking may reduce IGF-1 levels." (PMID 27598322, 2016). "Notably, intracellular presence of insulin is associated with adverse prognosis in human lung adenocarcinoma; High circulating IGF-1 levels are associated with increased risk of lung cancer, and inhibition of insulin/IGF-1 signaling inhibits growth of lung cancer cells." (PMID 20642846, 2010). "Our studies revealed that TM4SF4 upregulation enhanced OPN and IGF1 secretion in lung cancer cells 28, suggesting its role in modulating ICL expression." (PMID 41356204, 2026). "Klotho can inhibit the IGF-1/insulin and Wnt/β-catenin signaling pathways, promoting autophagy and apoptosis of lung cancer cells, thus exerting an inhibitory effect on tumor growth." (PMID 38287280, 2024). "Other evidence in lung cancer supports the critical role of the endoplasmic reticulum (ER) chaperone protein GRP78 in the response to IGF1 stimulation in TAMs." (PMID 38892104, 2024). "Studies have found that levels of HbA1c, C-peptide, and insulin-like growth factor-1 (IGF-1) are significantly higher in lung cancer patients than in healthy individuals." (PMID 39044884, 2024). "Lung cancer (LC) is regarded as a fatal cancer, and insulin-like growth factor 1 (IGF1) and its receptor (IGF1R) have been found to play a key role in regulating tumor glycolytic metabolism." (PMID 38840891, 2024). "While cortisol signaling is typically known for its protective effects in lung cancer through reducing inflammation, some studies show that GR can increase cell proliferation and metastases through the upregulation of IGF1, TGF-β, WNT, and Hippo pathways." (PMID 38912926, 2024). "In this context, we conducted MR analysis to determine the association between serum IGF-1 levels with asthma, COPD, lung cancers and IPF." (PMID 36936149, 2023). "Yu has reported that elevated serum levels of IGF-1 and decreased IGFBP-3 levels were positively associated with the risk of lung cancer." (PMID 36329881, 2022). "It was observed that the mRNA expression of EGFR, MAPK1, Akt1, and SRC were upregulated in the lung cancer tissues whereas the expression of IGF1 and PI3KR1 was reduced as compared to the normal lung tissues." (PMID 36313358, 2022). "In line with the results on VEGF secretion, MIA-690 alone reduced IGF-1 protein levels in PM tumors, suggesting direct effects, as previously demonstrated in both mesothelioma and lung cancer cells." (PMID 36232554, 2022). "The staining indicating expression levels were moderate to strong in all hub proteins except for IGF1, which was undetectable in lung cancer tissues compared to normal lung tissue." (PMID 36313358, 2022). "Metformin also induced a G1-cell cycle arrest and apoptosis in EML4-ALK(+) lung cancer (H3122) cells partly through the modulation of IGF-1 expression." (PMID 36017326, 2022). "Increased levels of IGF1 in blood were found in multiple cancers, including colon, breast, prostate, lung cancer, and pancreatic cancer." (PMID 35931675, 2022).